KITLG (KIT ligand)
Description:
Ligand for the receptor-type protein-tyrosine kinase KIT. Plays an essential role in the regulation of cell survival and proliferation, hematopoiesis, stem cell maintenance, gametogenesis, mast cell development, migration and function, and in melanogenesis. KITLG/SCF binding can activate several signaling pathways. Promotes phosphorylation of PIK3R1, the regulatory subunit of phosphatidylinositol 3-kinase, and subsequent activation of the kinase AKT1. KITLG/SCF and KIT also transmit signals via GRB2 and activation of RAS, RAF1 and the MAP kinases MAPK1/ERK2 and/or MAPK3/ERK1. KITLG/SCF and KIT promote activation of STAT family members STAT1, STAT3 and STAT5. KITLG/SCF and KIT promote activation of PLCG1, leading to the production of the cellular signaling molecules diacylglycerol and inositol 1,4,5-trisphosphate. KITLG/SCF acts synergistically with other cytokines, probably interleukins.
Synonyms: MGF; SCF; SF; Kitl; KL-1; FPH2; SLF; DFNA69; DCUA; FPHH; SHEP7; WS2F
Tractability: Small molecule: it has a binding pocket of medium quality. Antibody: UniProt places it where antibodies can reach, with high confidence; its Gene Ontology location is reachable by antibodies, with high confidence; UniProt predicts a signal peptide or a membrane-spanning region. PROTAC: ubiquitination databases record sites on it.
Target class: Secreted protein
Gene: Protein-coding gene on chromosome 12 (88,492,789 to 88,580,851, reverse strand). Ensembl gene ENSG00000049130.
Subcellular location: Cell membrane (Isoform 1); Cytoplasm (Isoform 2); Cytoplasm, cytoskeleton; Cell membrane; Cell projection, lamellipodium; Cell projection, filopodium; Secreted (Soluble KIT ligand)
Subcellular location (Human Protein Atlas): Vesicles
Pathways (Reactome):
Signal Transduction: PI5P, PP2A and IER3 Regulate PI3K/AKT Signaling; PIP3 activates AKT signaling; RAF/MAP kinase cascade; Regulation of KIT signaling; Signaling by SCF-KIT
Developmental Biology: Transcriptional and post-translational regulation of MITF-M expression and activity
Disease: Constitutive Signaling by Aberrant PI3K in Cancer
Gene Ontology:
Molecular function: protein binding; stem cell factor receptor binding; cytokine activity
Biological process: embryonic hemopoiesis; male gonad development; positive regulation of cell population proliferation; positive regulation of hematopoietic progenitor cell differentiation; cell adhesion; ovarian follicle development; signal transduction
Cellular component: cytoplasm; filopodium; lamellipodium; plasma membrane; extracellular region; cytoskeleton; membrane
Genetic constraint (gnomAD): Loss-of-function variants: 2 observed, 10.83 expected, observed/expected ratio (o/e) 0.18, 90% interval 0.074 to 0.58. The upper end of that interval is the gene's LOEUF score, 0.58, which puts it in group 2 of 6, group 1 being the genes least tolerant of losing a copy. Missense variants: 56 observed, 98.65 expected, observed/expected ratio (o/e) 0.57, 90% interval 0.46 to 0.71. Synonymous variants: 27 observed, 32.23 expected, observed/expected ratio (o/e) 0.84, 90% interval 0.62 to 1.15.
Gene-disease validity (ClinGen):
ClinGen rates the evidence that KITLG causes each of these diseases.
nonsyndromic genetic hearing loss (autosomal dominant): Limited.
Homologues: Orthologues: chimpanzee KITLG (100% identical), macaque KITLG (94% identical), dog KITLG (86% identical), rabbit KITLG (85% identical), guinea pig KITLG (83% identical), mouse Kitl (83% identical), rat Kitlg (82% identical), pig KITLG (75% identical), tropical clawed frog kitlg (35% identical), zebrafish kitlga (21% identical), zebrafish kitlgb (16% identical).
Diseases named in the same sentence as KITLG in open-access papers:
KITLG is named in the same sentence as 329 diseases in open-access papers, as found by Europe PMC text mining. Sharing a sentence is not in itself a finding about the gene and the disease. The quoted sentences say what the papers report.
melanoma (47 papers, 2000 to 2026). A malignant, usually aggressive tumor composed of atypical, neoplastic melanocytes. "Mutations in KITLG have been identified as a factor in the oncogenesis of melanoma in man." (PMID 35202309, 2022). "LEF1 is an outstanding candidate gene for melanoma susceptibility as it can regulate microphthalmia-associated transcription factor, KIT-ligand (KITLG), tyrosinase, and other melanogenic genes." (PMID 30744341, 2019). "Inactivating mutations of KIT lead to piebaldism, whereas activating mutations in KIT lead to melanoma and mutations in the KIT ligand (KITLG) cause the Steel phenotype in mice and progressive familial hyperpigmentation in humans." (PMID 28170433, 2017). "Recent GWAS have unveiled association between SNPs or genetic variants in MC1R, TPCN2, ASIP, KITLG, SLC24A5, TYR, IRF4, OCA2/HERC2, SLC24A4, SLC45A2, TYRP1, and pigmentation as well as melanoma." (PMID 21559390, 2011). "Interestingly, a study analysing the CNV of KITLG in blood samples from dogs with digital melanomas (n = 9) found 4–6 copies, with 4/5 of the dogs with a dark colour having >4 copies." (PMID 38787171, 2024). "Based on these data, we hypothesise that CNV of KITLG may be involved in the development of melanoma in dogs with dark and black coats." (PMID 35202309, 2022). "In this study, a meta-analysis of 11 nevus GWAS studies identifies novel SNPs in KITLG and 9q32, and bivariate analysis with melanoma GWAS meta-analysis reveals that most nevus genes affect melanoma risk, while melanoma risk loci do not alter the nevus count." (PMID 30429480, 2018). "In the case of KITLG, the variant most strongly associated with pigmentation (fair hair), rs12821256, modifies a distant enhancer, and was associated neither with melanoma or nevus count in our study (see Supplementary Results)." (PMID 30429480, 2018). "Overall, we conclude that most nevus genes affect melanoma risk (KITLG an exception), while many melanoma risk loci do not alter nevus count." (PMID 30429480, 2018). "Interestingly, the authors proposed that most genes that influence nevus count also modulate melanoma risk—with KITLG representing a notable exception—whereas many known melanoma risk loci do not affect nevus propensity." (PMID 41596618, 2026). "However, further analyses using a larger cohort and appropriate controls will be needed to validate that the CNV of KITLG could be involved in developing digital melanomas in dogs with dark-coloured coats." (PMID 38787171, 2024). "KITLG mutations have not been investigated in canine melanoma so far." (PMID 35202309, 2022). "Alleles which increase nevus number proportionately increase the risk of melanoma (Supplementary Results) with KITLG, the interesting exception is that the nevus-associated variants did not predict melanoma risk, rather, predisposing to other cancers (e.g., testicular germ cell)." (PMID 30429480, 2018). "KITLG/KIT signaling also has known roles in human melanoma as well as murine and zebrafish melanoma models." (PMID 37021774, 2023). "The hyperpigmentation phenotype due to overexpression of kitL resemble a human condition known as Familial Progressive Hyperpigmentation (FPH, MIM #145250) which is also due to gain of function mutations in KIT ligand and has not been associated with melanoma development." (PMID 21170325, 2010). "In addition, it may alter the motif of POU3F2, a transcription factor (TF) present in melanoma cell lines known to alter the expression of pigmentation genes (i.e. MITF, KITLG), although a recent study suggests that this TF does not have a role in normal skin melanocytes." (PMID 35712076, 2022).
breast cancer (35 papers, 2010 to 2025). A primary or metastatic malignant neoplasm involving the breast. "We prove that KITLG increases programmed cell death in breast cancer cells and augments apoptosis by stimulating the transcription of c-KIT genes." (PMID 38213737, 2024). "KITLG gene expression levels were evaluated in testicular germ cell cancer, breast cancer, and gastrointestinal stromal tumors." (PMID 34261404, 2021). "SCF and its receptor, c-kit ligand (KL), are up-regulated in particular human malignancies including gastrointestinal stromal tumor (GISTs), breast cancer, hematopoietic cell, myeloid leukaemia, and glioma." (PMID 25799412, 2015). "GLS, YY1AP1, FBXO22, KLC1, CUL4A, KITLG, and CYRIB are changed by AS that may be linked to the emergence of breast cancer." (PMID 40384436, 2025). "Conversely, in breast cancer, mast cells recruited and activated by tumor cells can induce transcriptional changes in genes such as SPP1, PDCD1, IL17A, TGFB1, KITLG, and IFNG, leading to anti-tumor effects." (PMID 40495762, 2025). "Our research demonstrated that overexpressing KITLG reduces proliferation, migration, and invasion in MDA-MB-231 breast cancer cells." (PMID 38213737, 2024). "For instance, elevated KITLG expression contributes to the carcinogenesis of uveal melanoma 18, neurofibromatosis type 1 19, gliomagenesis 20, breast cancer 21 and non-small-cell lung cancer 22, presumably because of the c-KIT/KITLG autocrine/paracrine stimulation-loop mechanism 23,24." (PMID 25213795, 2014). "Whereas studies in breast cancer cells have indicated that HIF-1α crucially regulates expression of stem cell factor (SCF), a c-KIT ligand, results on small-cell lung cancer cells indicated that activated SCF-c-KIT stimulated HIF-1α-mediated VEGF expression via PI3K/Akt activation." (PMID 26760782, 2016). "At least we were not able to detect an increased cell growth through SCF (c-kit ligand) application in previous experiments, whereas incubation with PDGF BB leads to augmented cell growth in all breast cancer cell lines and has the ability to stimulate cell migration." (PMID 20691121, 2010).
colorectal cancer (22 papers, 2013 to 2022). A primary or metastatic malignant neoplasm that affects the colon or rectum. "In the present study, we demonstrated a novel target of miR-34c, KITLG, which has been implicated in colorectal cancer (CRC)." (PMID 25213795, 2014). "Aberrant expression of KITLG by autocrine/paracrine stimulation mechanisms has been discovered in various cancers, such as colorectal cancer, non-small cell lung cancer, glioblastoma, and thymoma." (PMID 36233032, 2022). "KITLG is the ligand of the tyrosine-kinase receptor, which is demonstrated as a novel target of miR-34c that inhibited the growth and invasion of colorectal cancer cells." (PMID 32426279, 2020). "Stem cell factor (SCF, KITLG) is frequently overexpressed in colorectal cancer cells." (PMID 29495357, 2018).
Stroke (21 papers, 2012 to 2025). Sudden impairment of blood flow to a part of the brain due to occlusion or rupture of an artery to the brain. "Therapies using stem cell factor (SCF), also known as a c-Kit ligand, had great promise for treating ischemia for myocardial infarct and stroke, however clinical development for SCF was stopped due to toxic side effects including mast cell activation in patients." (PMID 37398327, 2023).
asthma (20 papers, 2006 to 2025). "Consistently, the reanalysis of blood samples demonstrated a significant upregulation of KITLG (the gene encoding SCF) expression in patients with severe asthma compared with those with moderate asthma and healthy controls." (PMID 40674143, 2025). "The reanalysis also revealed the coexpression of SCF (KITLG) and COL1A2 in human lung fibroblasts, confirming the expression of SCF in human fibroblasts during asthma." (PMID 40674143, 2025). "Similarly, KITLG expression was also higher in the sputum of patients with severe asthma compared with those with moderate asthma and healthy controls." (PMID 40674143, 2025). "Moreover, the study found an interaction between the KITLG gene and exposure to air pollution, suggesting that KITLG may play a role in asthma pathogenesis by modulating allergic inflammation." (PMID 41049290, 2025). "Increased levels of the KIT ligand, stem cell factor (SCF), were found in the serum of asthma patients as well as in the lungs of mice with allergic airway inflammation, with one study reporting SCF levels positively correlating with asthma severity." (PMID 40016948, 2025). "Many other pathways were also identified that are regulated by IL-13 and relevant to asthma pathogenesis (e.g. CCL17, CCL26, CTGF, FCER1A, KITLG, MUC2, NOS2, TLR3)." (PMID 29367592, 2018).
lung cancer (19 papers, 2011 to 2024). A malignant neoplasm involving the lung. "Moreover, KITLG (SCF) has been linked to CSC in prostate and lung cancer." (PMID 22894607, 2012).
anemia (18 papers, 2009 to 2025). A reduction in the number of red blood cells, the amount of hemoglobin, and/or the volume of packed red blood cells. "The discovery of the dimeric molecule SCF (also known as Kit Ligand, Steel Factor, or Mast Cell Growth Factor) and KIT was based on experimental single gene-induced anemias in mice which led to the identification of the W and Steel (Sl) loci." (PMID 28725969, 2018).
glioma (16 papers, 2006 to 2024). A benign or malignant brain and spinal cord tumor that arises from glial cells (astrocytes, oligodendrocytes, ependymal cells). "Reportedly, endogenous KITLG co-expression leads to activation of KIT receptors in glioma cell lines and other cancers." (PMID 22672386, 2012). "Importantly, a subset of these human-derived cytokines that included CXCL10, IL-33, CXCL8, KITLG, CCL2, and TGFα were not secreted or secreted at very low levels in vitro by BT147 cells, suggesting that the increased secretion was the result of a glioma–host cell interaction within the brain." (PMID 33020472, 2020).
colon carcinoma (13 papers, 2014 to 2025). "In addition, when using DLD-1, a colon cancer cell with a nearly 15 times lower expression of KITLG than HCT-116, we also did not observe co-cultured supernatant induced tumor-promoting effects." (PMID 39387546, 2024).
gastrointestinal stromal tumor (13 papers, 2006 to 2025). "Autocrine/paracrine KITLG-KIT and IGF1-IGF1R signaling are also activated in several cancers including gastrointestinal stromal tumors (GIST), the most common sarcoma." (PMID 24116170, 2013). "Currently, there are few studies investigating the molecular expression of KITLG and c-KIT in veterinary medicine, mostly in canine mast cell tumors and gastrointestinal stromal tumors, with no descriptions of specific immunolabeling in canine SCC or DSCC." (PMID 36851392, 2023).
diabetes (12 papers, 2009 to 2026). "These SNPs represent several distinct physiological pathways, including blood coagulation (F3), endothelial and hematopoietic stem cell proliferation (KITLG), protease pathways contributing to diabetes (CAPN10), and extracellular matrix remodeling (MMP2)." (PMID 19351393, 2009). "The analysis showed that the linear form of KITLG was upregulated in pregnant women with GDM compared to pregnant women without diabetes (median, [IQR]; 1.75 [1.17–2.39] vs. 0.76 [0.58–1.39], p = 0.02." (PMID 39000149, 2024).
Infertility (12 papers, 2015 to 2025). "This study was designed to create an experimental varicocele model by asimple surgical procedure in dog with minimum invasion and to investigate the effect ofvaricocele-induced infertility on the expression of six related genes (HSP90, HSP70, IL-4, TNF, KITLG and KIT receptor)." (PMID 28868836, 2017). "Overall, downregulationof KITLG/KIT-receptor, as reported in here,may be a critical factor in varicocele-mediated infertility.It has been documented that expression ofKIT is influenced by various cytokines during inflammationdepending on the model or type of thecell system used." (PMID 28868836, 2017).
melasma (12 papers, 2014 to 2025). "In the present study, the AOPT‐LTL treatment significantly inhibited the SCF/c‐KIT ligand/receptor pathway in the skin tissue of guinea pigs with melasma." (PMID 40916844, 2025). "The innovative mode of AOPT‐LTL effectively achieved the goal of reducing mast cell infiltration, angiogenesis, and inflammation in the skin tissue of melasma pigs, which may have been through the inhibition of the SCF/c‐KIT ligand/receptor pathway." (PMID 40916844, 2025). "AOPT‐LTL treatment significantly enhances the improvement of melasma by diminishing melanogenesis, inflammation, angiogenesis, mast cell infiltration, and collagen degeneration, potentially through the inhibition of the SCF/c‐KIT ligand/receptor pathway." (PMID 40916844, 2025).
ovarian carcinoma (12 papers, 2009 to 2023). A malignant neoplasm originating from the surface ovarian epithelium. "An exciting extension is the possibility of KITLG activation in ovarian cancer initiating cells (OCICs), as we recently reported upregulation of the KITLG receptor, c-kit/CD117, in this highly tumorigenic subpopulation of cells in human ovarian adenocarincomas." (PMID 19615063, 2009). "Interestingly, KITLG is an important regulator of ovarian surface epithelial cell growth, and up-regulation of KITLG expression has been reported in ovarian cancer." (PMID 19615063, 2009). "Taken together, these observations suggest that disruption of TGF-β signaling pathway may lead to altered KITLG expression, which in turn could contribute to ovarian cancer carcinogenesis." (PMID 19615063, 2009). "Our data show that bTAM preferentially express growth factors and cytokines known to promote ovarian cancer growth, progression and relapse, such as CCL18, but also factors, which have previously not been implicated in ovarian cancer progression, e.g. KITLG and complement factors." (PMID 29141914, 2018). "In two breast and one of two ovarian cancer cell lines having RBM10 KD, KITLG exon 6 was preferentially included, with normal RBM10 levels associated with exon 6 exclusion." (PMID 28728573, 2017). "With respect to ovarian cancer, KIT ligand (SCF) is anti-apoptotic and increases cisplatin resistance, whereas imatinib induces apoptosis." (PMID 24302925, 2013). "In addition, the microarray study has detected aberrant AS of genes in ovarian carcinomas, including FGFR2, DNNP3B, KITLG, MDM2 and MRP123." (PMID 34001978, 2021).
myocardial infarction (11 papers, 2013 to 2024). Gross necrosis of the myocardium, as a result of interruption of the blood supply to the area, as in coronary thrombosis. "Previously, we have shown that the c-kit ligand stem cell factor (SCF) can induce CSC migration into the infarcted area during myocardial infarction (MI)." (PMID 27245949, 2016). "For instance, KITLG administration via a lentiviral vector was reported to protect against myocardial infarctions, and the assay we used is clearly unsuitable to study a cardioprotective activity." (PMID 24672526, 2014).
endometriosis (10 papers, 2014 to 2025). The growth of functional endometrial tissue in anatomic sites outside the uterine body. "The aim was to evaluate the effects of curcumin on growth factors expression by evaluating Growth Differentiation Factor-9 (GDF-9), Kit Ligand (KitL), and Tumor Necrosis Factor α (TNFα) expressions in bovine cumulus-oocyte complexes (COC)s cultured with PF from infertile women with endometriosis." (PMID 31417983, 2018). "Endometriosis decreased AMH protein expression (p < 0.05 vs. Sham), although no significant changes were seen in KITLG (KL mRNA) or GDF-9 expression." (PMID 40002761, 2025).
pancreatic cancer (10 papers, 2006 to 2026). "These genes, AREG, CXCR4, IL11, KITLG and OSCAR, are known to play a significant role in tumour progression and metastasis promotion of prostate cancer as well as colorectal or pancreatic cancers." (PMID 39374163, 2025). "KIT is a proto-oncogene associated with several tumours that enhances proliferation and invasion of pancreatic cancer cell lines; KITLG/SCF and TPSAB1 are mast cell markers indicating an early infiltration of stroma surrounding PanINs with mast cells." (PMID 23372777, 2013).